PCA3 (prostate cancer associated 3)
Diseases named in the same sentence as PCA3 in open-access papers (continued):
Sharing a sentence is not in itself a finding about the gene and the disease.
acute myeloid leukemia (1 paper, 2022). Acute myeloid leukemia (AML) is a group of neoplasms arising from precursor cells committed to the myeloid cell-line differentiation. "For example, lncRNAs PCA3, PCGEM1, and PCAT-1 are highly expressed in prostate cancer, and the expression level of KIAA0125 correlated negatively with the prognosis of acute myeloid leukemia (AML)." (PMID 36591508, 2022).
lymph node metastasis (1 paper, 2025). "In this study, the characteristics of GC patients were examined, specifically the correlation between the expression pattern of CBR3-AS1 and PCA3 and various clinicopathological features, such as age, tumor size, sex, TNM staging, H. pylori infection, lymph node metastasis, and histology." (PMID 40356687, 2025).
metastatic disease (1 paper, 2023). "On the other hand, we have not detected any regulatory effects of PRUNE2/PCA3 in late genetic events such as prostate cancer progressing to biochemical recurrence, which includes the development of local tumor recurrence and/or the development of metastatic disease." (PMID 36645410, 2023).
pancreatic cancer (1 paper, 2018). "One of the most notable examples was in 1995 when the lncRNA PCA3 was discovered and has since become a diagnostic for pancreatic cancer." (PMID 30547845, 2018).
Pca (1 paper, 2022). "Prostate cancer antigen 3 (PCA3), a prostate-specific non-coding RNA, as a molecular detector for Pca has been approved by the Unite States Food and Drug Administration (FDA)." (PMID 36185200, 2022).
cancer (136 papers, 2008 to 2025). A tumor composed of atypical neoplastic, often pleomorphic cells that invade other tissues. "PCA3 levels in radical prostatectomy specimens were similarly linked to cancer aggressiveness in preliminary studies." (PMID 39188554, 2023). "Among the urinary tests, PCA3 is recommended for patients undergoing repeated biopsy and for the identification of the risk of a positive biopsy for high-grade cancer; this is probably due to its controversial correlation with aggressiveness." (PMID 36672713, 2023). "Prostate cancer–associated 3 (PCA3) and prostate cancer gene expression marker 1 (PCGEM1) were the first discovered cancer-associated lncRNAs." (PMID 33281872, 2020). "Among the characterized biomarkers one of the most promising for its diagnostic potential, is the Prostate Cancer gene 3 (PCA3)." (PMID 25651917, 2015). "This study was designed to systematically locate the regions of differential expression of these genes in single cross-sections of five cancerous prostates and evaluate whether the location of the carcinoma was associated with TMPRSS2-ERG or PCA3 mRNA levels or ERG protein expression." (PMID 26294063, 2015). "Our results demonstrate that specific EV RNAs, such as miR−141, miR−375, and PCA3 lncRNA, are effective in distinguishing PCa from non-cancer controls and in stratifying patients by tumour grade and stage." (PMID 41340217, 2025). "In the primary cancer samples, the expression of PCA3, ERG, NPY, and AMACR was significantly upregulated, making them the characteristic genes with the largest expression differences." (PMID 39988626, 2025). "Regarding PCA3, it was extensively studied in cancer and was found to be differentially expressed in the exosomes of cerebrospinal fluid of AD patients." (PMID 39086756, 2024). "Platelets isolated from glioma and prostate cancer patients contained cancer-related RNA biomarkers EGFRvIII and PCA3, respectively, paving the way for the new potential for cancer diagnostics." (PMID 37139159, 2023). "Among the most prominent examples of lncRNAs whose aberrant expression is associated with cancer development are the descriptions of MALAT1, HOTAIR, and PCA3." (PMID 38068923, 2023). "For distinguishing between cancer and non-cancer, a PCA3 cutoff at 35 copies/copy of PSA mRNA showed a specificity of 76% and a sensitivity of 50%, with an AUC of 0.68." (PMID 38201592, 2023). "One option is the MyProstateScore (MPS) test (LynxDx, Inc., Ann Arbor, MI), which combines urinary expression of prostate cancer antigen 3 (PCA3) and the TMPRSS2:ERG gene fusion (T2:ERG) with serum PSA to define the risk of GG ≥ 2 cancer." (PMID 36585434, 2023). "CCAT1 and PCA3 and HULC are using as non-invasive or minimally-invasive diagnostic biomarker using body fluids (urine/blood) for detection of cancer." (PMID 36428681, 2022). "Some of the lncRNA with good potential in cancer diagnosis or prognosis include PCA3, MALAT1, HOTAIR, H19, and CCAT1." (PMID 35892331, 2022). "The SERS signals for the RNA biomarkers T2:ERG and PCA3 in cancer patient urine samples were obtained by adsorbing T2:ERG and PCA3 amplicons onto 40 nm cationic silver nanoparticles." (PMID 34884946, 2021). "As PCA3 increases with cancer aggressiveness, tests based on it—Progensa PCA3, MiPS and ExoDx—show the ability to distinguish between cancers with high and low Gleason scores, indicating high utility in therapeutic decision-making." (PMID 34282798, 2021). "While decreased expression has been seen in CASC2 and PCA3 in cancer, these lncRNAs were down-regulated in G-CIMP-low suggesting their tumor suppressor potential." (PMID 33926464, 2021). "For example, MALAT1, which is highly expressed in most cancers, regulates the cell cycle, and PCA3 is an important molecular marker in the early stage of cancer." (PMID 34079798, 2021). "The first observed transcripts of altered expression in the tissue of a malignant tumor—prostate cancer—were PCA3 and PCGEM1." (PMID 34445129, 2021).
cancer (continued). "Due to its high expression in cancer cells, PCA3 is detectable in the urine and upon quantification can be used to generate a PCA3 score to predict biopsy outcome." (PMID 33799946, 2021). "On the other hand, lncRNA PCA3 is specifically overexpressed in most PCa cancer patients and has been approved by the FDA as a PCa diagnostic marker in the urine of PCa patients, but its use for assessing response to ADT in advanced PCa is limited." (PMID 33869227, 2021). "The LBXexo score demonstrated relatively greater sensitivity than PCA3 alone, with 85.7% vs. 71.4% for any-grade cancer and 100% vs. 87.5% for high-grade cancer." (PMID 32099679, 2020). "Unlike miRNA that is broadly expressed in most of cells, some lncRNAs, such as PCA3, are specifically expressed in cancer cells." (PMID 32122338, 2020). "The combination of phi and PCA3 was able to significantly improve cancer identification compared to only one biomarker." (PMID 32053990, 2020). "It is noteworthy that PCA3-based assays are still effective when cancer cells make up <10% of the examined sample." (PMID 33330574, 2020). "We first compared phi with PCA3 in 151 patients at initial biopsy, showing that phi and PCA3 were accurate predictors of cancer (AUC 0.77 and 0.71, respectively)." (PMID 32053990, 2020). "The AUC for the LBXexo score was 0.723 (95% CI 0.58–0.849, p=0.017) in predicting any-grade cancer, significantly higher than that of PCA3 alone and PSA (0.595, 95% CI 0.436–0.754, p=0.289)." (PMID 32099679, 2020). "A multi-center study of TMPRSS2:ERG (T2-ERG) and PCA3 in post-DRE urine from 1312 men showed significant improvement over serum PSA for the detection of clinically-relevant cancer at biopsy." (PMID 31013716, 2019). "We also updated data regarding PCA3 interactions with cancer-related miRNAs and expression in other tissues and diseases beyond the prostate." (PMID 31762940, 2019). "The PCA3/PRUNE2 duplex undergoes A-to-I editing at multiple sites by ADAR1, which leads to reduced levels of PRUNE2, increased PCA3 expression levels and, thereby, a subsequent increase in cancer cell proliferation, adhesion and migration." (PMID 30585209, 2018). "This induction is quite reasonable, as studies have indicated that the RT-PCR based PSMA level in urine was superior to PCA3 in predicting cancer." (PMID 28293631, 2017). "We saw upregulation of PCA3 (average 2.1 fold) and PCA3-shRNA2 (average 1.5 fold) in men with an eventual diagnosis of cancer, when compared to those with only benign histology." (PMID 28380027, 2017). "To begin to explore the prostate-specific expression of PCA3, we evaluated publically available The Cancer Genome Atlas (TCGA) data finding that while PCA3 was expressed in very few samples from other cancers, it was most abundant in prostate cancer." (PMID 28881605, 2017). "More than 95% of PCa specimens show PCA3 over-expression, and in addition to cancer tissue, PCA3 transcripts have also been identified in urine samples of patients with benign enlargement and malignant disease of the prostate." (PMID 28275218, 2017). "We did find a trend towards upregulation of PCA3-shRNA2 in cancer, suggesting underpowering of the sample size." (PMID 28380027, 2017). "Our results included some well-known cancer-associated lncRNAs such as HOTAIR, PCA3, PCAT1, and CRNDE." (PMID 27147563, 2016). "The first lncRNA identified in 1999, DD3 (PCA3), is extremely specific to PC and shows overexpression in >95% of cancer patients." (PMID 26690121, 2015). "Molecular changes outside the carcinoma foci are also indicated for PCA3, as its expression was only moderately increased in the carcinoma regions." (PMID 26294063, 2015). "We studied the extent and location of the mRNA expression of two suggested prostate cancer markers, TMPRSS2-ERG fusion gene and PCA3, in a systematic way in cross-sections of cancerous prostates containing both histologically benign and carcinoma areas." (PMID 26294063, 2015).
cancer (continued). "It would therefore seem that the increase in PCA3 mRNA expression is not limited to the carcinoma foci in a cancerous prostate, but rather that there is a more global field change." (PMID 26294063, 2015). "The statistically significant difference in median PCA3 mRNA values between carcinoma samples and HB samples was 3.6-fold (p < 0.001)." (PMID 26294063, 2015). "PCA3 expression was detected in all five cross-sections, with statistically significant, three-fold higher expression in carcinoma regions." (PMID 26294063, 2015). "A recent study using the novel TMA-based urine assay showed that combining PCA3 and gene fusion results has markedly different risks of cancer, high-grade cancer, and clinically significant cancer upon biopsy." (PMID 23304520, 2012). "The CD26+ cancer cells also had elevated expression of prostate cancer-associated genes AMACR (α-methylacyl-CoA racemase), HPN (hepsin) and PCA3 (prostate cancer antigen 3)." (PMID 20021671, 2009). "PCA3 is detectable in urine, making it non-invasive, an attractive attribute for cancer biomarkers." (PMID 40004558, 2025). "For instance, lncRNA PCA3 has emerged as a promising biomarker for early prostate cancer detection, and the aberrant expression of lncRNA MALAT1 in cancer cells underlines its potential as a therapeutic target in cancer treatment." (PMID 39827195, 2025). "ExInAtor was modeled on 1112 whole genomes from 23 cancer types deposited in GENCODE, and predicted 15 lncRNA drivers with a high confidence, of which nine were novel lncRNAs and six were known cancer-related transcripts, including PCA3, MALAT1, BCAR4, lncRNA-ATB, and SAMMSON." (PMID 38068923, 2023). "Next, for PRUNE2 expression, PCA3 expression, and their ratio, we regrouped the cancer cases according to whether the values were greater than (deemed ‘high’) or less than/equal to (deemed ‘low’) their respective mean values." (PMID 36645410, 2023). "Some lncRNAs may serve as biomarkers for cancer detection, metastasis and survival of patients, and the prostate cancer specific lncRNA, prostate cancer antigen 3 (PCA3) is an FDA approved lncRNA biomarker for prostate cancer detection." (PMID 32326624, 2020). "The molecular mechanism of cancer caused by upregulation of HOTAIRM1 and PCA3 in ATC still remains unknown." (PMID 32760219, 2020). "It has also been found that among various cancer-related genes, PCA3 could differentiate biopsy positive patients from those negative using RNA isolated from exosomes." (PMID 31762940, 2019). "For cancer diagnosis, a well-known example is prostate cancer antigen 3 (PCA3)." (PMID 31406486, 2019). "In EVs, PCA3/actin was 0.32 in cancer patients, but -2.21 in BPH patients." (PMID 29584777, 2018). "In sediments, PCA3/actin was 2.33 in cancer patients, but 2.59 in BPH patients." (PMID 29584777, 2018). "For example, prostate cancer gene 3 (PCA3) is the first prominent biomarker of lncRNAs." (PMID 28781594, 2017). "Prostate cancer gene 3 (PCA3) is the first prominent example of lncRNAs as a novel biomarker." (PMID 27322075, 2016). "Repressive chromatin-associated lncRNAs also includeseveral lncRNAs (PCA3, GAS6-AS1, CECR7 and BDNF-AS1)that have been implicated in cancer or other cellular functions, and among thisBDNF-AS1 lncRNA has been shown to regulate gene expression by recruitingPRC2 (refs 30, 52,53, 54)." (PMID 26205790, 2015). "The consensus in most studies is that PCA3 is often correlated with insignificant PCa and tumor volume, yet, in the clinically significant cancers, there is no definite evidence for an association with histopathologic prognostic factors." (PMID 26339615, 2015). "In addition to overexpression in tumours, increased expression of PCA3 has been described also in areas adjacent to carcinoma foci and the phenomenon was explained by a carcinogenic field effect." (PMID 26294063, 2015).
cancer (continued). "Thus was identified the promising biomarker PCA3 (prostate cancer gene 3) by differential display comparing cancer with normal and benign hyperplasia prostate specimens." (PMID 23840433, 2013). "Three other markers (PSMA, HPN, GALNT3) plus PCA3, for example, could distinguish cancer from benign at 100% in one report." (PMID 23029164, 2012). "PCA3 is expressed at high levels in metastatic PCa but, empirical data do not support an association between PCA3 upregulation and clinical stage, Gleason scores, tumour volume, pathological stage or cancer progression." (PMID 24281110, 2010). "Novel genetic markers (such as Transmembrane protease serine 2 (TMPRSS2)-ERG fusion gene mRNA) or prostate cancer gene 3 (PCA3) had already entered the clinical practice, raising the question whether subsequent protein changes impact the evolution of the disease and the response to treatment." (PMID 28061466, 2017). "Most of them measured either cancer-related proteins (i.e., PSMA, PCA3, TMPRSS2:EGR, or PSA) or exosomal cell surface proteins (CD9, CD3, EpCAM, or CD81)." (PMID 39859516, 2025). "One of the multiparametric tests, the MiPS (Michigan Prostate Score) includes analysis of PCA3, TMPRSS2/ERG and serum PSA to improve detection of high-grade cancers." (PMID 40115018, 2025). "This was based on morning first catch (non-DRE) urine and generated the following AUCs for the presence of any cancer: ERG 0.782, PCA3 0.783, PSMA 0.772, CK19 0.731, EpCAM 0.739." (PMID 38730670, 2024). "For example, cancer RNA biomarkers such as KRAS, PCA3, PIK3CA mutants, EGFRvIII, FOLH1, KLK2, KLK3, EML4-ALK, and NYP have been reported to be sequestered by platelets that actively uptake tumor-derived material." (PMID 39274207, 2024). "The combination of PCA3 and PHI was able to significantly improve cancer identification compared to the use of only one biomarker." (PMID 36672713, 2023). "Editing by ADAR1 at multiple sites in the PCA3/PRUNE2 duplex results in a reduction of PRUNE2, and an increase in PCA3 expression, therefore increasing in cancer cell the ability of cancer cell, such as proliferation, adhesion and migration." (PMID 35898396, 2022). "Among the lncRNAs known so far, PCA3 is the first and only lncRNA to receive Food and Drug Administration (FDA)-approval as a cancer biomarker test to date." (PMID 36649030, 2022). "The biofunction “development of carcinoma” was one of the top cancer-related enriched biofunctions (p-value of 0.0176), with 8 DE lncRNAs: PVT1, CASC2, PCA3, EPB41L4A-AS1, C10orf25, CYTOR, FOXD2-AS1, and CRNDE." (PMID 33926464, 2021). "Oncogenic lncRNAs in human cancer, including HOTAIR, MALAT1, PCA3, CASC15, and CASC20 are also annotated in dogs." (PMID 33194754, 2020). "The lncRNA prostate cancer antigen 3 (PCA3) is one of the most specific PCA biomarkers, being significantly upregulated in cancer compared with healthy prostate." (PMID 28241429, 2017). "The algorithm based on the analysis of ERG, PCA3 and SPDEF showed its advantages in discriminating the high-grade cancer (≥GS7) from low-grade malignancy (GS6) and benign disease than tPSA in CaP screening." (PMID 28938580, 2017). "PCA3 mRNA expression can be detected in urine samples from men with PCa and has a higher specificity than PSA for cancer detection (PROGENSA assay,)." (PMID 28380027, 2017). "It has been suggested that urinary PCA3 and TMPRSS2:ERG fusion tests and serum PHI correlate to cancer aggressiveness-related pathological criteria at prostatectomy." (PMID 25079439, 2014). "The combination of PCA3 and PSMA EV RNA generated the highest AUC of 0.870 for any cancer." (PMID 38730670, 2024). "PCA3 expression, which is 60- to 100-fold greater in cancerous than in benign prostate tissues, gives the gene a cancer specificity, which is not the case for PSA." (PMID 38201592, 2023). "Aside from PCA3, no other lncRNA has been approved by the FDA for diagnostic, prognostic, or treatment response prediction in any type of cancer." (PMID 38068923, 2023).